KLF15 (KLF transcription factor 15)
Diseases named in the same sentence as KLF15 in open-access papers (continued):
Sharing a sentence is not in itself a finding about the gene and the disease.
heart failure (continued). "KLF15 mRNA expression decreased more in the hypertrophied hearts that progressed to heart failure compared to control and compensated rats, suggesting that expression of KLF15 may play a role in the prevention of heart failure." (PMID 29702551, 2018). "KLF15 is highly expressed in metabolically active tissues (e.g., heart, skeletal muscle, and liver), and previous work from our group has shown that cardiac KLF15 expression is induced with fasting and significantly attenuated in rodent and human samples of heart failure." (PMID 25815008, 2015). "The fact that KLF15 is consistently down-regulated in animal models of hypertrophy and human heart failure may suggest that KLF15 is not a just a response to heart failure, but that loss of KLF15 may actually contribute in the disease progression." (PMID 22586493, 2012). "Cardiac KLF15 mRNA was significantly reduced with LVH and decreased further with the development of heart failure." (PMID 29702551, 2018). "The genetic findings complement the human studies which reported reduced KLF15 expression in the hearts of patients with LVH and heart failure." (PMID 29702551, 2018). "Notably, several transcription factors highlighted by our approach, such as FOXC1 in heart failure and KLF10 and KLF15 in ischemic cardiomyopathy, are supported by existing literature, validating our approach." (PMID 38673810, 2024). "The adjusted risk of heart failure hospitalization was 5.5-fold greater in those with LVH and the KLF15 rs9838915 A allele compared to the group with no LVH and the GG genotype." (PMID 28400202, 2017). "Mice lacking KLF15 are not only sensitized to the development of hypertrophy and heart failure, but they also develop severe fibrosis." (PMID 22586493, 2012). "Crucial roles of the Kruppel-like factor-15 (KLF15), a member of the KLF family of transcription factors, has attracted much attention in controlling muscular homeostasis, notably under pathological conditions such as diabetes, Duchenne muscular dystrophy, and heart failure." (PMID 39795113, 2024).
breast carcinoma (13 papers, 2017 to 2024). "MSP analysis showed that the KLF15 promoter was methylated in 3/9 (about 30%) breast cancer cell lines." (PMID 36347994, 2022). "Collectively, these results indicate that KLF2 and KLF15 induce cell cycle arrest and cell apoptosis in breast cancer." (PMID 35033064, 2022). "Although the prognostic signatures based on KLFs expression have been investigated in several studies, we found that both KLF2 and KLF15 can be used as prognostic predictors independent on other KLFs in patients with breast cancer." (PMID 35033064, 2022). "The transwell and scratch assays indicated that overexpression of KLF2 or KLF15 inhibited breast cancer cell migration)." (PMID 35033064, 2022). "Together, these results indicate that KLF2 and KLF15 function as tumor suppressors in breast cancer." (PMID 35033064, 2022). "As the results showed that KLF15 is significantly downregulated in breast cancer cell lines and tissues, which promoter methylation of KLF15 partially contributes to." (PMID 36347994, 2022). "The MTT and colony formation assays indicated that overexpression of KLF2 or KLF15 inhibited breast cancer cell proliferation." (PMID 35033064, 2022). "KLF15 expression and methylation were detected by RT-qPCR, RT-PCR and methylation-specific PCR in breast cancer cell lines and tissues." (PMID 36347994, 2022). "Consistent with previous study, we demonstrated that KLF2 and KLF15 inhibits breast cancer proliferation and migration." (PMID 35033064, 2022). "The results showed that both KLF2 and KLF15 expression was significantly lower in breast cancer cell lines, especially in the triple-negative breast cancer cell lines CAL51 and MDA-MB-231." (PMID 35033064, 2022). "Given low KLF15 expressions, we analyzed promoter methylation status of KLF15 among breast cancer patients with samples gathered from TCGA using online tools." (PMID 36347994, 2022). "Intra-family comparison showed no matter how much other KLFs expressed, both KLF2 and KLF15 expression levels can distinguish RFS of patients with breast cancer independent other KLFs expression levels." (PMID 35033064, 2022). "We next performed in vitro experiments to assess the effect of KLF2 and KLF15 on the biological behaviors in breast cancer cells." (PMID 35033064, 2022). "We firstly determined the expression levels of KLF2 and KLF15 in different breast cancer cell lines and the normal breast cell line by RT-PCR and western blot." (PMID 35033064, 2022). "KLF2 and KLF15 function as tumor suppressors in breast cancer and are potential biomarkers for prognostic prediction in patients with breast cancer." (PMID 35033064, 2022). "We next employed GSEA analysis to explore the relevant signaling pathways of KLF2 and KLF15 high expression group and low expression group in patients with breast cancer." (PMID 35033064, 2022). "Taken together, these results suggest that KLF2 and KLF15 can be used as prognostic predictor in patients with breast cancer." (PMID 35033064, 2022). "KLF15 has been shown to decrease proliferation in a variety of cancer cells, including pancreatic cancer, endometrial cancer, and breast cancer." (PMID 35345512, 2022). "For example, KLF15 has shown anti-proliferative activities in gastric and breast cancer cells; however, KLF15 promotes the proliferation and metastasis of lung adenocarcinoma cells." (PMID 33080033, 2020). "In the human breast cancer-derived cell line T47D, KLF15 has been reported to decrease estrogen-dependent cell proliferation." (PMID 28388563, 2017). "KLF15, as a member of the KLF family, has been linked to increased tumor growth in pancreatic, endometrial and breast cancers, likely the results of its role in promoting cell proliferation." (PMID 29299121, 2017). "Moreover, KLF15 suppressed breast cancer cell proliferation and induced cell cycle arrest by up-regulation of p21." (PMID 35033064, 2022).
breast carcinoma (continued). "Finally, in vitro experimental validation was confirmed KLF2 and KLF15 functioning as tumor suppressors, resulted in the inhibition of cell proliferation and migration in breast cancer." (PMID 35033064, 2022). "Furthermore, our results showed that KLF2 or KLF15 can be used as a prognostic factor independent on the other KLFs in patients with breast cancer." (PMID 35033064, 2022). "Our study demonstrated that KLF2 and KLF15 function as tumor suppressors, may serve as prognostic biomarkers in patients with breast cancer." (PMID 35033064, 2022). "Next, we assessed whether KLF2 or KLF15 overexpression in breast cancer cells can influence breast cancer proliferation and migration by KLF2- or KLF15-transfected MDA-MB-231 cells." (PMID 35033064, 2022). "Finally, we investigated the effect of KLF2 and KLF15 on biological behavior of breast cancer cells in vitro." (PMID 35033064, 2022). "Furthermore, we demonstrated that KLF2 and KLF15 can function as tumor suppressors in breast cancer." (PMID 35033064, 2022). "In summary, the dysregulation expression of KLF2 and KLF15 in breast cancer tissues might play an important role in BC oncogenesis." (PMID 35033064, 2022). "For example, KLF15 has been suggested to be a novel tumor suppressor in breast cancer." (PMID 34572749, 2021). "In the current study, we aimed to investigate the role of KLFs in breast cancer progression and found that the expression of KLF2 and KLF15 can be used as the prognostic predictor in patients with breast cancer." (PMID 35033064, 2022). "Kruppel like factor 15 (KLF15), a transcriptional factor belonging to the Kruppel-like factor (KLF) family of genes, has recently been reported as a tumor suppressor gene in breast cancer." (PMID 36347994, 2022). "Homo sapiens (hsa)-miR-4262 has been reported to participate in paclitaxel resistance in non-small cell lung cancer by regulating PTEN, and it promotes the proliferation and invasion of human breast cancer cells directly by targeting kruppel-like 6 (KLF6) and KLF15." (PMID 33821195, 2021).
renal fibrosis (12 papers, 2017 to 2025). A final common manifestation of a wide variety of chronic kidney diseases characterized by glomerulosclerosis and tubulointerstitial fibrosis. "Taken together, these results suggested that KLF15 hypermethylation-induced loss of KLF15 accounted for fibroblasts activation and renal fibrosis." (PMID 40490444, 2025). "Hence, hypermethylation of KLF15 not only explains its loss in fibrotic kidneys, but also results in progress of renal fibrosis." (PMID 40490444, 2025). "In a CKD mice model, an invalidation of KLF15 was associated with an increased renal fibrosis." (PMID 33352729, 2020). "And in renal pathophysiological processes, KLF15 was reported to be involved in podocyte differentiation, mesangial proliferation, inflammatory response and renal fibrosis." (PMID 40490444, 2025). "Among the differentially methylated regions (DMRs), we screened KLF15, which was reported to ameliorate renal fibrosis and fibroblast activation." (PMID 40490444, 2025). "To gain insights into the role of KLF15 hypermethylation on renal fibrosis, we investigated its methylation and expression both in vivo and in vitro." (PMID 40490444, 2025). "Inhibition of HDAC11 attenuates renal fibrosis, blocks the pro-fibrogenic response induced by Ang II through interaction with activator protein 2 to activate KLF15 transcription." (PMID 36339432, 2022). "Here we report that the histone deacetylase HDAC11 promotes renal fibrosis by epigenetically repressing the transcription of KLF15, an anti-fibrogenic factor." (PMID 32363192, 2020). "An increasing number of studies have demonstrated a critical role for KLF15 in the kidney, involving tubular physiology, podocyte injury, renal fibrosis, and mesangial pathology." (PMID 31523196, 2019). "In this review, we focused on KLF15 role in kidney biology and highlighted its role as a protective factor against podocyte injury, renal fibrosis, and other pathological processes." (PMID 31523196, 2019). "Herein, we provide an update on the research literature regarding the role of KLF15 on renal fibrosis." (PMID 31523196, 2019). "Present studies on the role of KLF15 in kidney biology mainly focus on podocyte injury, mesangial pathology, and renal fibrosis." (PMID 31523196, 2019). "Combined with in vitro experiments, these results confirmed that KLF15 was critical in attenuating renal fibrosis by inhibiting the canonical Wnt/β-catenin pathway." (PMID 31523196, 2019). "Interestingly, some studies have reported that KLF15 mitigates renal fibrosis and injury in hypertensive mice, which is in line with our observations in intestinal tissues." (PMID 39135690, 2024). "Mechanistically, KLF15 may regulate renal fibrosis by suppressing the ERK/MAPK, the JNK/MAPK, and the Wnt/β-catenin pathways." (PMID 32363192, 2020). "The KLF15 downregulation and renal fibrosis are reversed with dietary protein restriction in mice." (PMID 33352729, 2020). "Interestingly, another report demonstrated that a low-protein diet increased renal KLF15 expression levels in normal and 5/6-nephrectomized rats, a remnant kidney model of progressive renal fibrosis." (PMID 31523196, 2019). "KLF15 is expected to be a potential therapeutic target for glomerular diseases and renal fibrosis." (PMID 31523196, 2019). "Therefore high ANG II levels expected in CHF and the decreased RPO2 we observed in our studies could promote renal fibrosis in part by suppression of KLF15, KLF4, and E--Cadherin." (PMID 36091359, 2022). "Kruppel-like factor 15 (KLF15) is a transcription factor that has been shown to suppress UUO and Ang II induced renal fibrosis in mice." (PMID 32363192, 2020). "Excitingly, a recent report showed that podocyte-specific induction of Klf15 in ADR-induced and HIV-1 transgenic (Tg26) proteinuric murine models, can attenuate renal fibrosis, inflammation and podocyte injury, contributing to improved cell survival." (PMID 31523196, 2019).
renal fibrosis (continued). "KLF15 is a kidney-enriched nuclear transcription factor previously shown to mediate renal physiological processes and pathologic progression of CKD, involving podocyte differentiation, tubular physiology, mesangial pathology, and renal fibrosis 34,35,54." (PMID 36632460, 2023). "Kruppel-like factor 15 (KLF15), a regulator of renal fibrosis, may play an anti-fibrotic role by inhibiting ERK/MAPK, TNK/MAPK, Wnt/β-catenin, and other pathways." (PMID 36148005, 2022). "Mei and colleagues were among the first to report that KLF15 levels were decreased in the kidneys of rats in a model of chronic renal disease (CKD) and that KLF15 deletion sensitized the mice to the development of renal fibrosis." (PMID 32363192, 2020). "Since the vicinity of the KLF15 promoter may contain AP-2α binding sites, the formation of the HDAC11- AP-2α complex inhibits KLF15 mRNA and protein levels, and the expression of collagen I, α-SMA, and other genes was increased, thus promoting the progression of renal fibrosis." (PMID 36148005, 2022). "Besides, knockdown of Klf15 in Foxd1+ stroma cells exacerbated the proliferation of myofibroblasts and the deposition of extracellular matrix in UUO and angiotensin II-treated mice, two murine models of renal fibrosis." (PMID 31523196, 2019).
diabetes (11 papers, 2010 to 2025). "In stage 2, the association of KLF15 SNPs with LVH was investigated in the Genetics of Diabetes Audit and Research in Tayside Scotland (Go-DARTS) type 2 diabetes cohort (n = 5631)." (PMID 28400202, 2017). "These include transcription factors concerned with the control of: adipogenesis (Pparγ, Klf15, Irf1, Creb1, Egr2, Gata3); lipogenesis (Mlxipl, Srebp1c); inflammation (Jun, Stat3); insulin signalling and diabetes susceptibility (Foxo1, Tcf7l2)." (PMID 21187013, 2010). "We used a 2-stage approach; Stage 1 examined the association between the 2 common KLF15 haplotype tagging SNPs in Caucasian patients with type 2 diabetes and no known cardiac disease who were prospectively recruited for an echocardiographic assessment (Melbourne Diabetes Heart Cohort, Australia)." (PMID 28400202, 2017). "This abundance in KLF15, in turn, increases the rate of diabetes-induced muscle atrophy through its ability to affect downstream target genes and code for protein catabolism." (PMID 36685197, 2022). "KLF15 was recently shown to contribute to diabetes-induced muscle atrophy, and the abundance of Klf15 mRNA was found to be increased in skeletal muscle of the immobilized mouse limbs." (PMID 35290243, 2022). "The role of KLF in muscle atrophy was further proved in KLF-15 knock-out mice, which were resistant to diabetes-induced skeletal muscle mass decline." (PMID 36685197, 2022). "The identification of the glucose-KLF15-BCAA regulatory circuit has potential implications in the cardiac remodeling of patients with diabetes or metabolic disorders." (PMID 30050148, 2018). "CMT is a progressive disease, and elevated blood glucose levels associated with diabetes mellitus may further reduce muscle mass through the action of two proteins, WWP1 and KLF15." (PMID 40951209, 2025). "The upregulation of KLF15 in hyperglycemia leads to the activation of genes involved in protein catabolism and muscle atrophy, highlighting KLF15 as a potential therapeutic target for managing skeletal muscle decline in diabetes mellitus." (PMID 39925192, 2025). "Given our prior description of a KLF15-PPARα molecular module regulating fatty acid oxidation, KLF15 may also play a role in diabetes-induced cardiac dysfunction." (PMID 29408889, 2018). "Studies are now needed to characterize the functional importance of these results, to understand the biological mechanisms involved, and to determine if the KLF15 SNP rs9838915 A allele is associated with LVH in patients without diabetes." (PMID 28400202, 2017). "We recently showed that the abundance of KLF15 in skeletal muscle is increased in response to hyperglycemia as a result of suppression of its ubiquitination by the E3 ubiquitin ligase WWP1, which in turn contributes to the development of skeletal muscle atrophy in diabetes mellitus." (PMID 35290243, 2022). "Furthermore, studies in mice have shown that hyperglycemia, a central disease of diabetes, promotes muscle atrophy via the WWP1/KLF15 pathway and that in mice lacking KLF15, specifically in the skeletal muscle, hyperglycemia-induced muscle atrophy is suppressed." (PMID 39693147, 2024).
Hyperglycemia (11 papers, 2020 to 2025). An increased concentration of glucose in the blood. "This particular mechanism was confirmed in a streptozotocin-induced diabetic model, in which mice deficient in muscle-specific KLF15 showed protection against hyperglycemia-induced skeletal muscle atrophy, while streptozotocin treatment in wild-type mice showed muscle atrophy." (PMID 39433511, 2024). "In addition, it has been reported that hyperglycemia is linked with muscle atrophy via a WW domain containing E3 ubiquitin protein ligase 1 (WWP1)/Krüppel-like factor 15 (KLF15) pathway." (PMID 32784808, 2020). "WWP1 is an endogenous E3 ligase that is known to prevent muscle atrophy during hyperglycemia by particularly targeting the Krüppel-like factor 15 (KLF15) protein, leading to the UPP-dependent KLF15 degradation." (PMID 39433511, 2024). "The expression of KLF15 has been found to be up-regulated in the livers of diabetic mice, and hyperglycemia is known to up-regulate KLF15 protein, thereby accelerating skeletal muscle atrophy." (PMID 35846289, 2022). "Hyperglycemia downregulates enzymes involved in catabolism of branched chain amino acids via inhibition of Krüppel-like factor 15 (KLF15), leading to intracellular accumulation of BCAAs, mTOR overactivation, and cardiomyocyte hypertrophy." (PMID 33712058, 2021). "Hyperglycemia was recently shown to promote skeletal muscle atrophy via the induction of KLF15, which is regulated by WW domain-containing E3 ubiquitin protein ligase 1 (WWP1) or cAMP-PKA/CREB signaling." (PMID 34571935, 2021). "Various molecular pathways have been identified in which high glucose levels play a significant role in hyperglycemia-induced muscle degradation, with the key role of the ubiquitin-proteasome pathway (UPP) and WWP1/KLF15 pathway." (PMID 39433511, 2024). "Hyperglycemia results in the downregulation of WWP1, thereby preventing WWP1-mediated degradation of KLF15 in skeletal muscle of old diabetic animals." (PMID 38129384, 2023). "Hyperglycemia inhibits degradation of KLF15 via downregulation of WWP1 and increased KLF15 promotes proteolysis via upregulation of atrogin-1 and MuRF1." (PMID 32784808, 2020). "Hence, the intricate relationship between hyperglycaemia, WWP1/KLF15 and diabetes-related WWP1 downregulation underscores the complex factors contributing to skeletal muscle atrophy, shedding light on potential mechanisms across various contexts." (PMID 38129384, 2023).